CGAS (cyclic GMP-AMP synthase)
Diseases named in the same sentence as CGAS in open-access papers (continued):
Sharing a sentence is not in itself a finding about the gene and the disease.
tumor (continued). "The precise activation of the cGAS-STING pathway for effective tumor immunotherapy remains a significant challenge due to the complexity of immune responses and tumor microenvironment (TME) limitations." (PMID 42261811, 2026). "We analyze its expression landscape across large patient cohorts, uncover its frequent silencing via promoter hypermethylation, and demonstrate that restoring cGAS–STING signaling revives innate immunity and selectively inhibits ecDNA+ tumor growth." (PMID 41509453, 2026). "Among the top-ranked variants were rs11554776, rs78233829, and rs7380824 in STING1, which demonstrated functional impacts on intrinsic cGAS-STING1-IFN signaling in cancer cells and potential influences on tumor immunity." (PMID 41569853, 2026). "Clinically, heightened cGAS-STING activity correlates with improved survival and enhanced responsiveness to immune checkpoint blockade in subset of tumor types." (PMID 42311657, 2026). "cGAMP is a key element of the cGAS-STING pathway, exerting its effects both as an intracellular second messenger and through export to neighboring cells within the tumor microenvironment." (PMID 40770563, 2026). "It elucidates how radiotherapy activates systemic antitumor immunity by inducing immunogenic cell death, activating the cGAS-STING pathway, upregulating MHC-I expression, and remodeling the tumor microenvironment." (PMID 41789104, 2026). "cGAS-STING signaling can promote antitumor immunity, and tumor cell STING is suppressed in a variety of cancer subtypes that resist immune checkpoint blockade." (PMID 42069723, 2026). "YbNano functions as a dual activator of cGAS/STING and TLR9, orchestrating dendritic cell activation and amplifying downstream innate and adaptive immune responses in tumor microenvironment." (PMID 41851580, 2026). "For example, hepatic tumor cells possess the ability to take up NETs, thereby activating the cGAS-STING pathway and inhibiting tumor migration." (PMID 41601699, 2026). "Meanwhile, TGR-BLDHs successfully evoked potent antitumor effects by activating the cGAS/STING pathway in both antigen-presenting and cancerous cells, eventually inhibiting tumor progression in vivo." (PMID 41678601, 2026). "Mechanistically, miR-32-5p activates the cyclic GMP-AMP synthase (cGAS)-stimulator of interferon genes (STING) signaling pathway through ARID1B down-regulation, ultimately remodeling the tumor immune microenvironment." (PMID 41608526, 2026). "Crucially, administration of Pseudomonas sterile supernatant was sufficient to activate cGAS-STING signaling, induce ICD, and inhibit tumor growth in microbiota-depleted mice." (PMID 41981755, 2026). "LZU‐WZLYCS01 intracellularly releases A2, which targets MAD2L1 to activate the cGAS‐STING pathway and induce tumor cell apoptosis." (PMID 41168906, 2026). "This review untangles the safeguards that prevent cGAS from recognizing nuclear self-DNA, delineates the antitumor and pro-tumor mechanisms of the cGAS-STING axis, and surveys tumor immunotherapy strategies targeting this pathway." (PMID 41881950, 2026). "In the tumor microenvironment (TME), stress-induced mitochondrial DNA (mtDNA) leakage activates the mtDNA-cyclic GMP-AMP synthase (cGAS)- stimulator of interferon genes (STING) axis, which exerts a “double-edged sword” role in tumor immunity." (PMID 41601699, 2026). "Restoring cGAS or STING in human and murine ecDNA+ cancer cells reactivates innate immune signaling and selectively suppresses ecDNA+ tumor growth in an immunocompetent mouse model." (PMID 41509453, 2026). "Quantitative real-time polymerase chain reaction analysis showed that PCD@Cu significantly upregulated the expression of Cgas, CCL5, and CXCL10 in tumor tissues, indicating that PCD@Cu activated the cGAS/STING pathway." (PMID 41424843, 2026).
tumor (continued). "NIR-II photothermal therapy and ROS-mediated oxidative stress induce immunogenic cell death (ICD), which, combined with cGAS-STING pathway activation, promotes dendritic cells (DCs) maturation and T cell infiltration for primary tumor regression." (PMID 41909233, 2026). "Remarkably, chronic activation of the CGAS-STING1 pathway due to CIN rewires signaling in cancer cells, creating a pro-metastatic tumor microenvironment." (PMID 40463121, 2025). "We discuss how aberrant R-loop formation influences key inflammatory pathways, including the cGAS–STING axis and NF-κB signaling, and their subsequent effects on tumor progression." (PMID 40629041, 2025). "The cGAS-STING pathway is a complex series of events that involves DCs detecting irradiated DNA and engulfing the irradiated tumor cells or internalizing irradiated tumor-derived exosomes, both of which eventually lead to the production of type-I IFNs." (PMID 40937253, 2025). "Cancer cells suppress the cGAS/STING pathway during tumor development and progression, leading to tumor immune evasion." (PMID 39975558, 2025). "Cytosolic DNA, derived from genomic instability or mitochondrial dysfunction, activates cGAS-STING signaling, which influences both tumor suppression and progression." (PMID 40507791, 2025). "Cytosolic mtDNA then activates the cGAS–STING pathway, triggering type I interferon (IFN) production and enhancing the cross-presentation of tumor antigens by dendritic cells (DCs)." (PMID 41425089, 2025). "Given that HCC is a solid tumor characterized by severe TME hypoxia, however, the teniposide-induced activation of the cGAS-STING pathway is significantly inhibited by hypoxia-inducible factor 1α (HIF-1α), thus contributing to a “cold” tumor." (PMID 40098962, 2025). "This disruption leads to the accumulation of cytoplasmic telomeric DNA fragments that are recognized by DCs, thereby activating the cGAS-STING pathway, promoting IFN-I production, and enhancing T cell-mediated anti-tumor immunity." (PMID 40333779, 2025). "Acting through the cGAS-STING pathway and an IL-15-dependent mechanism to activate NK cells and CD8+ lymphocytes, ONP-302 reduced tumor growth in models based on classical immunotherapy." (PMID 41007722, 2025). "Nuclear DNA damage, mtDNA release or DNA mediated by bacteria or viruses facilitates the canonical cGAS–STING pathway, triggering IFN expression and anti‐tumour immunity." (PMID 41275427, 2025). "Collectively, the classical pathway and cGAS/DRP1 axis provide dual regulatory perspectives on ferroptosis, offering novel therapeutic strategies for modulating cell death in tumours." (PMID 41275427, 2025). "The cytosolic mtDNA then activates the cGAS/STING signaling pathway, triggering a type I interferon response, which enhances CD8+ T cell infiltration and anti-tumor immunity and increases sensitivity to PD-1 inhibitors." (PMID 41154773, 2025). "Radiotherapy has been reported to activate the cGAS–STING pathway, thereby enhancing anti-tumor immunity." (PMID 40355720, 2025). "cGAS-STING-targeted therapies hold significant potential in oncology but are limited by challenges such as toxicity, tumor resistance, delivery barriers, and irAEs." (PMID 40052963, 2025). "Activation of the cGAS-STING pathway following the release of mtDNA serves as a potent DAMP, helping to bridge the gap between tumor cell death and immune system activation." (PMID 40299564, 2025). "This process effectively activates the cGAS-STING pathway, demonstrating potential for preventing tumor recurrence and metastasis in HCC." (PMID 41438738, 2025). "The results showed that the nanoformulation was 66.2% more effective than either drug alone in reducing tumor growth, suggesting that the synergistic effect of PPI and Mn2+ enhances the cGAS–STING-mediated immune response." (PMID 40486836, 2025).
tumor (continued). "It profoundly influences TIME through various mechanisms: it methylates the Arg133 site of cGAS, suppressing its dimerization and activity, thereby blocking the cGAS-STING pathway and downstream interferon responses, which weakens anti-tumor immunity." (PMID 41154773, 2025). "Mitochondria-targeted drugs induce tumor mtDNA oxidation and specific release into the cytoplasm, activating the cGAS-STING pathway and affecting tumor immune-related responses." (PMID 41246345, 2025). "For tumors with high CIN, where cGAS-STING is persistently activated, inhibiting the pathway can prevent tumor progression." (PMID 40052963, 2025). "cGAS-STING pathway activation induces multiple antitumor effects, including immune response activation, interferon production, and tumor cell death." (PMID 41220920, 2025). "Type I interferon outputs from cGAS–STING activation support dendritic-cell maturation and cross-priming, enhancing T-cell–mediated tumor immunity." (PMID 41373427, 2025). "The cyclic GMP-AMP synthase–stimulator of interferon genes (cGAS-STING) pathway activation enhances immune responses and reshapes the tumor microenvironment to support immune activation." (PMID 40052963, 2025). "Enhancing DC function can significantly improve anti-tumor immunity, and activation of cyclic GMP-AMP synthase-stimulator of interferon genes (cGAS-STING) pathway represents one of the most effective strategies." (PMID 40548402, 2025). "They generate double-stranded DNA by cleaving damaged endogenous or exogenous DNA, triggering the activation of the innate immune pathways such as cGAS-STING-IFN, and enabling the body to produce anti-viral or anti-tumor immune responses." (PMID 39759116, 2025). "TREX2 degrades cytosolic DNA, repressing cGAS-STING activation, leading to less apoptosis of tumor cells and downregulated CD8+ T cell infiltration in the TME, ultimately enhancing resistance to immunoblockade therapy." (PMID 41373022, 2025). "Strikingly, Trim6 deletion activated the cGAS-STING pathway and simultaneously inhibited tumor progression in MSS malignancies." (PMID 40817248, 2025). "These mtDNA fragments are subsequently engulfed by immune cells within the TME, activating the cGAS-STING pathway and amplifying anti-tumor immunity." (PMID 40621423, 2025). "Knockdown of S100A2 activates the cGAS/STING pathway, suppressing tumor cell viability and invasiveness, suggesting that S100A2 typically inhibits this pathway." (PMID 39949780, 2025). "In the context of cancer, the cGAS-STING signaling exhibits a dual nature, exerting anti-tumor effects through the induction of IFNs while, paradoxically, fostering tumor progression in certain scenarios via the promotion of chronic inflammation." (PMID 41142804, 2025). "TREX1 has a protumorigenic effect by inhibiting the cGAS-STING-mediated immune activation within and outside the tumor and by limiting checkpoint activation of the adaptive immune response in the tumor microenvironment." (PMID 40581636, 2025). "Among them, the cGAS-STING signaling pathway plays a dual role in tumor immunity: it can suppress anti-tumor immunity to promote cancer progression, or enhance tumor antigen presentation to exert an anti-tumor effect." (PMID 41246345, 2025). "At the same time, activation of the cGAS–STING pathway induces full maturation of DCs and induces death of CD8+ T cell-sensitive and CD8+ T cell-resistant tumor cells by simultaneously increasing CD8+ T cell and NK cell activity." (PMID 40486836, 2025). "Stimulating the cGAS-STING pathway can affect the occurrence and development of HCC and reduce the tumor burden in advanced HCC." (PMID 40098962, 2025).
tumor (continued). "cGAS-STING axis activity promotes every step of T cell immune defenses against cancer, effectively turning an immunologically “cold” tumor into a “hot” tumor being targeted by multiple immune responses." (PMID 40552295, 2025). "The PtMnIr induce ferroptosis by downregulating GPX4 and promoting LPO, while simultaneously activating the cGAS-STING pathway through Mn2+ release, which sensitizes tumor cells to innate immune responses." (PMID 40846966, 2025). "Tumors with intact cGAS-STING signaling often exhibit spontaneous T cell infiltration and inflammatory gene signatures, correlating with “hot” tumor phenotypes that respond favorably to immunotherapy." (PMID 40981069, 2025). "Conversely, in the context of established HCC, short-term stimulation of the cGAS-STING cascade has demonstrated the ability to diminish tumor load in advanced HCC and reconfigure the TME, thereby augmenting anti-tumor immunity." (PMID 40098962, 2025). "Following uptake by cancer cells and immune cells alike, LDHs-cGAMP-TAAs initiate the cGAS-STING signaling cascade, resulting in the generation of IFN-I, CXCL10, and other molecules that enhance CTL infiltration into the tumor." (PMID 40098962, 2025). "One of the key immune evasion mechanisms driven by chronic cGAS-STING activation is the up-regulation of immune checkpoint molecules, particularly PD-L1, which leads to T-cell exhaustion and impaired anti-tumor immunity." (PMID 40052963, 2025). "Some previous studies have examined the role of the cGAS–STING pathway in CAFs and its positive effect on the activation of the anti-tumor immune response." (PMID 40451897, 2025). "The cGAS-STING pathway serves as a primary sensor for cytosolic DNA, initiating type I interferon responses and enhancing anti-tumor immunity." (PMID 40673277, 2025). "CAR-Ms selectively engulfed NKG2DL+ tumor cells, polarized to an M1 phenotype, and activated PI3K-AKT and cGAS-STING pathways, driving phagocytosis and pro-inflammatory cytokines secretion." (PMID 41388305, 2025). "Cytosolic viral nucleic acids simultaneously activate cGAS–STING and RIG-I pathways, producing interferon-stimulated genes that attract and mature BATF3+ dendritic cells within the tumor microenvironment." (PMID 41440025, 2025). "qPCR analysis of the tumor tissue demonstrated that the expressions of DNA damage marker genes (TP53BP1, PARP1, and BRCA1), cGAS, STING, SEI1, and PD‐L1 were increased in melphalan or bortezomib treated mice." (PMID 40135791, 2025). "In the classical STING signaling pathway, pathogen DNA, Cyclic Dinucleotides (CDNs) substances, tumor dsDNA, or aberrant cytosolic mtDNA are recognized by cyclic GMP-AMP (cGAMP) synthase (cGAS), which then catalyzes the formation of cGAMP from GTP and ATP." (PMID 40008133, 2025). "cGAS-STING activation enhances tumor immunogenicity and primes the tumor microenvironment for checkpoint inhibitors." (PMID 40552295, 2025). "Tang and colleagues engineered a tumor microenvironment (TME)-responsive MnO2-melittin nanoparticle (M-M NPs) that activates the cGAS-STING pathway, promotes the maturation of antigen-presenting cells, and initiates systemic anti-tumor immune responses." (PMID 39861694, 2025). "The topoisomerase II inhibitor teniposide mediates the cGAS-STING axis and induces tumor immunogenicity by inducing the release of high-mobility group box 1 (HMGB1) and type I IFN signaling in tumor cells." (PMID 40643531, 2025). "i) cGAS-STING Pathway Activation: Oxygen-vacancy-engineered CBNO-OV1 nanosheets generate ROS under ultrasound, inducing tumor cell necroptosis and releasing cytosolic dsDNA." (PMID 40521198, 2025). "In contrast to other metallic elements that activate the cGAS–STING pathway, platinum compounds exhibited immunomodulatory effects on the TME, promoting the release of tumor neoantigens and facilitating the expanded secretion of antigen-presenting cells." (PMID 40486836, 2025).
tumor (continued). "Extensive research over the past decade has established the cGAS–STING axis as a central regulator of innate immunity and tumor immune responses." (PMID 41204180, 2025). "However, their impact on tumor cell-intrinsic cGAS–STING expression remains unclear." (PMID 40451897, 2025). "It strongly activated the cGAS–STING pathway, providing a promising pharmacological approach to prevent tumor recurrence and metastasis." (PMID 40486836, 2025). "These in vivo results are highly in agreement with the in vitro data, thereby demonstrating that the cGAS‐STING pathway is crucial for OMVs‐ and IR700‐modified OMV‐mediated tumour suppression, potentially via activation of the systemic antitumour immunity." (PMID 40240911, 2025). "This highlights the dual-edged nature of cGAS-STING pathway modulation, underscoring the need for careful therapeutic targeting to balance the beneficial triggering of anti-tumor immunity and potentially detrimental pro-tumorigenic effects." (PMID 40986050, 2025). "Radiotherapy acts as an in situ vaccine, inducing immunogenic cell death and activating the cGAS-STING pathway to stimulate type I interferon (IFN-α/β) production, which enhances dendritic cell maturation and tumor antigen presentation." (PMID 41438748, 2025). "The cGAS-STING pathway’s role in cancer is complex, functioning as both a tumor suppressor and promoter." (PMID 39949780, 2025). "Expression of TCF1 is further enhanced via cGAS–STING–dependent IFN-I signaling, ensuring robust proliferation and activity of tumor-specific CD8+T cells." (PMID 41204180, 2025). "Sustained cGAS-STING activation persistently produces pro-inflammatory cytokines, which support immune evasion and promote tumor cell proliferation." (PMID 40052963, 2025). "Radiotherapy kills cancer cells via inducing non­repairable DNA damage, resulting in the accumulation of cytosolic dsDNA in tumor cells, which can activate the STING signaling pathway through cGAS recognition." (PMID 40842018, 2025). "Literature suggests dysregulation of these pathways induces cytosolic DNA accumulation, activating the cGAS-STING pathway and recruiting CD8+ T cells into the tumor microenvironment to elicit antitumor immunity." (PMID 40919158, 2025). "Intravenous administration of the nanomedicine resulted in an increase in localized enrichment of metformin and Mn2+ in cancer cells, both of which synergistically upregulated the cGAS-STING pathway and enhanced T cell tumor-killing ability." (PMID 39776799, 2025). "Collectively, these mechanisms highlight the pivotal involvement of cGAS–STING pathway in modulating programmed cell death, offering a valuable therapeutic target to counteract tumour immune evasion." (PMID 41275427, 2025). "This triggers the activation of the cGAS-STING signaling pathway, which stimulates immune responses targeting the tumor." (PMID 40299564, 2025). "By coordinating these processes, the cGAS–STING pathway functions as an essential link connecting innate and adaptive immunity, thereby enabling the establishment of strong and lasting anti-tumor responses." (PMID 41204180, 2025). "MMP NDs exploit the synergistic redox activity of high-valence Mo/Mn to deplete tumor-overexpressing GSH, induce ferroptosis, and activate the cGAS-STING pathway to amplify antitumor immunity." (PMID 40846966, 2025). "Analyses revealed that the commercially available cGAS‐STING agonist ADU‐S100 and the small molecular tether 5BThi were relatively ineffective in inducing an IFN‐I response in tumor cells." (PMID 39999304, 2025). "Its deletion also leads to the escape of DNA breakage in tumor cells, producing more single-stranded DNA (ssDNA), which is then recognized by the cyclic GMP-AMP synthase (cGAS) protein, activating the cGAS-STING signaling pathway to induce IFN-I production." (PMID 40342423, 2025).